FOXM1 (forkhead box M1)
Diseases named in the same sentence as FOXM1 in open-access papers (continued):
Sharing a sentence is not in itself a finding about the gene and the disease.
hepatocellular carcinoma (158 papers, 2008 to 2026). A malignant tumor that arises from hepatocytes. "HIF-1α-induced FOXM1 expression has been linked to increased resistance to apoptosis in cancers like hepatoma, contributing to tumor progression." (PMID 39594778, 2024). "Further machine learning (LASSO, RF, and SVM-RFE algorithms) analysis found that seven immune infiltrating cells were significantly associated with patients with hepatocellular carcinoma in the FOXM1 expression subgroup." (PMID 37234166, 2023). "In hepatocellular carcinoma, this trimeric complex containing FOXM1 was also associated with increased expression of genes responsible for aneuploidy and chromatin instability—features known to enhance tumorigenic potential." (PMID 37686402, 2023). "FOXM1 is frequently upregulated in the majority of human solid cancers and is highly associated with poor clinical prognosis, including but not limited to hepatocellular carcinoma and lung adenocarcinoma." (PMID 34740322, 2021). "FOXM1 is associated with several human carcinomas, and alterations in FOXM1 signaling are correlated with carcinogenesis and oncogenesis in gliomas, prostate, lung, colorectal, breast, and hepatocellular cancers." (PMID 37821870, 2023). "In hepatocellular carcinoma, a long non-coding RNA-encoded peptide PINT87aa could induce cellular senescence by blocking FOXM1-mediated PHB2." (PMID 35646056, 2022). "FoxM1, a member of the conserved forkhead box transcription factor family, is involved in cell cycle regulation, DNA damage repair, and apoptosis and has been associated with the development of breast, pancreas, and liver carcinomas." (PMID 36431766, 2022). "FOXM1 has been implicated in hepatocellular carcinoma (HCC) progression, but the underlying molecular mechanism remains elusive." (PMID 31072351, 2019). "Finally, silencing of FoxM1 expression could inhibit human hepatocellular carcinoma growth, and FoxM1 has been reported an underlying therapeutic target because it can be presented to cell surface by tumor cells." (PMID 27351282, 2016). "FOXM1, GLUT1, and STAT3, other oncogenic transcription factors, are commonly associated with hepatocellular carcinoma, where activated STAT3 is proposed to regulate the expression of FOXM1 and GLUT1." (PMID 40713647, 2025). "The oncogenic transcription factor FOXM1 is significantly overexpressed in numerous cancer types, including pancreatic, lung adenocarcinoma, and hepatocellular carcinoma." (PMID 39897042, 2025). "A study on hepatocellular carcinoma has also shown that FOXM1 is involved in promoting the process of immune cell infiltration in tumors." (PMID 40566633, 2025). "For instance, XTP8 was confirmed to be highly expressed in hepatocellular carcinoma, and promoted the proliferation and inhibited apoptosis of hepatocellular carcinoma cells by up-regulating the expression of FOXM1." (PMID 38717641, 2024). "For example, FOXM1 can promote the progression of hepatocellular carcinoma by upregulating KIF4A expression." (PMID 38937742, 2024). "The induction of UBE2S in hepatocellular carcinoma cells is attributed to the transcription factor FOXM1." (PMID 38312603, 2024). "Among them, BTF3 promotes the proliferation of hepatocellular carcinoma and gastric cancer cells by up-regulating FOXM1." (PMID 39707202, 2024). "The transcription factor FOXM1 induces the upregulation of UBE2S in hepatocellular carcinoma cells, leading to the ubiquitination of PTEN at Lys327, Lys 60 and the phosphorylation of AKT, which enhances chemoresistance." (PMID 38312603, 2024). "The abnormally high expression of UBE2S was found to promote resistance of hepatocellular carcinoma cells to oxaliplatin and 5-FU via the FOXM1/UBE2S/PTEN/p/AKT axis." (PMID 38312603, 2024). "According to a prior study, FOXM1-induced upregulation of TYMS promotes the progression of hepatocellular carcinoma." (PMID 38719775, 2024).
hepatocellular carcinoma (continued). "Another member of the KIF2C family, KIF4A, is regulated by the transcription factor FOXM1 and has been shown to promote hepatocellular carcinoma cell proliferation." (PMID 38250721, 2024). "FOXM1 has been demonstrated to bind to PINT87aa, inducing cellular senescence and promoting hepatocellular carcinoma (HCC) progression." (PMID 38976093, 2024). "Several exclusive reviews have emphasized the role of FoxM1 and FoxOs in ovarian cancer and hepatocellular carcinoma, respectively." (PMID 37821870, 2023). "While FOXM1 has been shown to promote hepatocellular carcinoma (HCC) progression, its transcriptional mechanisms remain incompletely understood." (PMID 38001498, 2023). "Dysregulation of miR-23b-5p promotes cell proliferation via targeting forkhead box M1 (FOXM1) in hepatocellular carcinoma." (PMID 36609391, 2023). "Forkhead box protein M1 (FOXM1), a master transcription factor for cell growth and proliferation, is closely associated with hepatocellular carcinoma, prostate cancer, glioma, and basal cell carcinoma." (PMID 35712491, 2022). "Patients with hepatocellular carcinoma also exhibited an upregulation of FOXM1 and resistance to regorafenib, which were correlated with a poor survival rate." (PMID 35887129, 2022). "A previous study showed that HBx activated the transcription of FoxM1 to promote HBx-mediated HCC metastasis, while FoxM1 inhibition significantly decreased HBx-enhanced hepatoma cell invasion in vitro and lung metastasis in vivo." (PMID 35784274, 2022). "Previous literature reported that SR9009 manifested marked selectivity for LXRα (also known as NR1H3) when compared with REV-ERBα, and LXRα suppressed FOXM1 expression in hepatocellular carcinoma." (PMID 36357378, 2022). "Cell viability experiments were conducted to detect the inhibitory effect of FOXM1-PROTAC on Hepatoma cell HepG2." (PMID 36171633, 2022). "LncRNA SLC2A1-AS1 affects aerobic glycolysis and progression by inhibiting STAT3/FOXM1/GLUT1 signaling pathway in hepatocellular carcinoma." (PMID 35090515, 2022). "Subsequently, it was found that FOXM1 overexpression in hepatoma cells can promote the cell cycle transition from S phase to G2/M phase and accelerate the cell cycle by regulating cell cycle genes such as, CDC25B and CyclinB1." (PMID 36171633, 2022). "Although the direct regulation of FOXM1 by LXRα was validated in hepatocellular carcinoma and macrophages, our study validated this regulation in PCa and provided a novel therapeutic strategy for targeting the FOXM1 pathway and PCS1 subtype." (PMID 36357378, 2022). "FoxM1 depletion in hepatocellular carcinoma quenched carcinoma mobility and triggered immunoreaction by activating specific CD8+ T killing." (PMID 36301031, 2022). "The lncRNA SLC2A1-AS1 is able to regulate aerobic glycolysis and development of hepatocellular carcinoma by inhibiting the STAT3/FOXM1/GLUT1 signaling pathway." (PMID 35874626, 2022). "We identified a close relationship between FOXM1 expression and regorafenib resistance, which was correlated with the survival of patients with hepatocellular carcinoma." (PMID 35887129, 2022). "The downregulation of FOXM1 mRNA expression was previously reported in atypical teratoid/rhabdoidtreated cancer by domatinostat and similarly in hepatocellular carcinoma by the pan-HDACi vorinostat." (PMID 35241126, 2022). "The upregulation of Linc-ROR and FOXM1 has been reported to impair the sensitivity of hepatocellular carcinoma cells to sorafenib." (PMID 34447693, 2021). "The knockdown of FOXM1 in human hepatocellular carcinoma (HCC) cell lines significantly alleviated cell cycle arrest and cell growth suppression." (PMID 34539442, 2021). "In hepatocellular carcinoma, FOXM1 regulates aerobic glycolysis by transactivating GLUT1 expression." (PMID 34740322, 2021). "The elevated expression of FOXM1 was observed in several aggressive human cancers, including breast cancer, hepatocellular carcinoma, colorectal cancer, and GC." (PMID 34073071, 2021).
hepatocellular carcinoma (continued). "For instance, PRDX2 enhances the proliferation and tumorigenicity of hepatoma cells by regulating the ERK/FoxM1/cyclin D1 signal axis." (PMID 34384442, 2021). "Previously, our study demonstrated that histone deacetylase inhibition (HDACi) sensitizes hepatocellular carcinoma cells (HCC) to oxidative stress through FOXM1 suppression." (PMID 34335925, 2021). "In hepatocellular carcinoma cell lines, FOXM1 was previously observed to transcriptionally activate long intergenic non-protein coding RNA regulator of reprogramming (Linc-ROR)." (PMID 34447693, 2021). "FoxM1 overexpression in hepatocellular carcinoma is reflective of tumor aggressiveness and recurrence, poor prognosis and low survival in patients." (PMID 34900697, 2021). "Moreover, several studies have demonstrated that high FOXM1 expression is associated with poor prognosis of patients with cancer having various tumors, including colorectal cancer, pancreatic ductal adenocarcinoma, hepatocellular carcinoma, non-small cell lung cancer, ovarian cancer, and GC." (PMID 34073071, 2021). "Activation of FOXM1 via the altered KRAS signaling has been evident in the development of hepatocellular carcinomas and initiation of lung tumorigenesis in RAS driven tumors." (PMID 33680951, 2020). "Recent in vitro evidence reveals an indispensable role of CCNB1 in the proliferation of human hepatocellular carcinoma cells, which is driven by forkhead box protein M1 (FOXM1)." (PMID 32775402, 2020). "FOXM1 leads to tumorigenesis resulting in various cancers including breast, colorectal, gastric, hepatoma, and lung cancers." (PMID 33142744, 2020). "For example, upregulation of USP39 in hepatocellular carcinoma contributes to the growth of SMMC-7721 cells via regulating the pre-mRNA splicing of FoxM1." (PMID 33255748, 2020). "Casticin promoted FOXO3a dephosphorylation and FOXM1 inactivation, leading to growth suppression and cell cycle arrest in hepatocellular carcinoma cells." (PMID 31952105, 2020). "Recently, a report demonstrated that UHMK1 expression was drived by an oncogene called yes-associated protein 1 (YAP1), a key factor in Hippo signaling pathway, through a combination effect of FOXM1 in hepatoma." (PMID 32580279, 2020). "USP39 regulates the growth of hepatocellular carcinoma cells via regulating the transcriptional factor FoxM1." (PMID 30898977, 2019). "For example, overexpression of miR-214 inhibits proliferation and migration in hepatocellular carcinoma by targeting FOXM1." (PMID 31844419, 2019). "Aberrant expression of FOXM1 plays an essential role in hepatocellular carcinoma, however, FOXM1 itself was only numerically reduced by D60, implying either post-transcriptional regulation or indirect involvement of FOXM1." (PMID 31249595, 2019). "FOXM1 expression was found to be upregulated in several tumors such as gastric cancer, hepatocellular carcinoma, lung caner, glioma and also colorectal cancer." (PMID 29416616, 2018). "They demonstrated that the FOXO3A-p27Kip1 pathway in hepatocellular carcinoma cell lines was activated by treatment with Casticin, as well as downregulation of FOXM1 which decreases FOXO3A expression." (PMID 30627573, 2018). "Inhibition of the mevalonate pathway by statins, inhibitors of 3-hydroxy-3-methylglutaryl CoA reductase (HMGCR), resulted in reduced expression of FoxM1 and increased cell death in human hepatoma cells." (PMID 29765517, 2018). "In this study, inhibition of HMGCR by statins resulted in not only increased cell death but also the reduced expression of FoxM1 in human hepatoma cells." (PMID 29765517, 2018). "Administration of pitavastatin significantly reduced the FoxM1 protein expression in a dose-dependent manner in these hepatoma cell lines." (PMID 29765517, 2018). "A previous report showed that the activation of LXRα resulted in the downregulation of FoxM1 and the suppression of proliferation in human hepatoma cells." (PMID 29765517, 2018).
hepatocellular carcinoma (continued). "For instance, it has been recently shown that the transcription factor Forkhead Box M1 (FOXM1) is a major player along hepatocellular carcinoma development driven by YAP overexpression." (PMID 29088718, 2017). "The ERK/CREB pathway was reported to be involved in FoxM1-mediated hepatoma cell invasion and lung metastasis." (PMID 29285247, 2017). "Recent studies demonstrated that elevated FOXM1 expression is found in a wide variety of cancers, including breast, ovarian, colon, liver, pancreatic and gastric cancers; Ewing sarcoma; hepatocellular carcinoma, and cervical cancer." (PMID 26918606, 2016). "For mmu-miR-6366, we found that FoxM1 (forkhead box M1) was potentially involved in proliferation, invasion and migration in mouse hepatocellular carcinoma cell lines." (PMID 27419627, 2016). "Recent studies demonstrated that ectopic FOXM1 activation increased Snail activity through AKT signaling in hepatocellular carcinoma cells isolated from FoxM1b Tg;Arf−/− mice." (PMID 25935853, 2015). "Extracelluar signal regulated kinase (ERK), promotes proliferation in many tissues and its activity is sustained by FOXM1 in hepatocellular carcinoma cells." (PMID 26075743, 2015). "Intriguingly, FoxM1 knockout mice fail to form hepatocellular carcinoma in a carcinogenic induction model, suggesting that FoxM1 is necessary for tumor initiation in the liver." (PMID 23404835, 2013). "Inhibition of FoxM1, combined with oxaliplatin treatment, significantly promoted the senescence of hepatocellular carcinoma cells." (PMID 24148180, 2013). "For example, overexpression of FoxM1 partially protected cancer cells against thiazole antibiotic-mediated cell death and enhanced hepatoma cell resistance to TNF-α–induced apoptosis." (PMID 24148180, 2013). "Furthermore, research showed that miR-3677-3p binds to FBXO31 and inhibit its expression in hepatitis B-associated hepatocellular carcinoma, this inhibition causes FOXM1 to be less ubiquitinated and degraded, which in turn encourages the growth of HCC and sorafenib resistance." (PMID 40303979, 2025). "Forkhead box protein M1 (FOXM1) is a master transcription factor for tumor cell growth and proliferation, which is related with several malignant tumors, including glioma, prostate cancer and hepatocellular carcinoma 66-68." (PMID 39991581, 2025). "Moreover, STMN1 has been demonstrated to be essential for FoxM1-mediated proliferation of cancer cells, such as hepatocellular carcinoma cells, gastric cancer cells and colorectal cancer cells." (PMID 38698443, 2024). "The malignant phenotype of hepatocellular carcinoma could be promoted by the FOXM1/UBE2S/PTEN/p/AKT axis, indicating that it may be possible to treat this disease by targeting UBE2S." (PMID 38312603, 2024). "Overexpression of miR-342-3p has been shown to suppress proliferation, migration, and invasion by targeting FOXM1 in cervical cancer and has also been shown to suppress hepatocellular carcinoma proliferation through the inhibition of the IGF-1R-mediated Warburg effect." (PMID 37958433, 2023). "USP39 has been reported to positively regulate FOXM1 expression in hepatocellular carcinoma." (PMID 37957720, 2023). "USP39 has been reported to positively regulate FOXM1 expression in hepatocellular carcinoma cells." (PMID 37957720, 2023). "FOXM1 is now used in the clinic as a prognostic and predictive marker for stage and grade of bladder cancer, and has been identified as the most significant prognostic factor for overall survival in patients with hepatocellular carcinoma." (PMID 37370117, 2023). "CCNB1, CCNE2, and FOXM1 were three other genes that were differentially expressed in more than one carcinoma with survival implications, specifically in kidney clear cell and liver carcinoma." (PMID 37345032, 2023).
hepatocellular carcinoma (continued). "Western Blotting results revealed that FOXM1 is also highly expressed in cell lines of other cancers besides hepatocellular carcinoma, which could be effective models for follow-up studies and related research." (PMID 36171633, 2022). "FOXM1 promoter is transcriptionally activated by CTCF in hepatocellular carcinoma." (PMID 35378133, 2022). "In addition to the role of FOXM1 in cell cycle progression, a recent study showed that FOXM1 is a master regulator of hepatocellular carcinoma metastasis by inducing EMT and increasing cell migration by transcriptionally activating STMN1." (PMID 36151566, 2022). "lncRNA MFI2-AS1 promotes hepatocellular carcinoma progression by the miR-134/FOXM1 axis." (PMID 35756697, 2022). "Lines of evidence implicate CENPF and FOXM1 may have novel co-operative roles in driving hepatocellular carcinoma (HCC)." (PMID 35865168, 2022). "In addition, lncRNA MALAT1 modulated miR-125a-3p to increase FOXM1 expression, resulting in hepatocellular carcinoma progression." (PMID 33539420, 2021). "However, our model of hepatoma AS-30D has similarities in the expression patterns for normal and cancer tissues for genes as FoxM1, Met, and especially Spp1." (PMID 34737944, 2021). "FOXM1 promotes hepatocellular carcinoma progression by regulating KIF4A expression." (PMID 33261584, 2020). "In hepatocellular carcinoma, FoxM1 could regulate cell cycle arrest, and the expression of cyclin B1, p27, and cyclin D1 was all changed in FoxM1 knock out MHCC-97H cells." (PMID 29554906, 2018). "Consequently, the upregulation of FOXM1 promotes the proliferation of hepatoma cells and enhances their resistance to apoptosis." (PMID 30208972, 2018). "FoxM1 is an oncoprotein that is significantly overexpressed in many malignancies including hepatocellular carcinoma, but its role in intrahepatic cholangiocarcinoma (ICC) remains unclear." (PMID 30580327, 2018). "Together, these data suggested that the mevalonate pathway could regulate the transcriptional activity of FoxM1 in human hepatoma cells." (PMID 29765517, 2018). "Taken together, these results indicated that the regulation of FoxM1 expression in the mevalonate pathway might be mainly through protein geranylgeranylation in human hepatoma cells." (PMID 29765517, 2018). "One possible explanation for this discrepancy might be that the role of these Rho family proteins in the downstream of the mevalonate-FoxM1 pathway might differ in cell death of human hepatoma cells." (PMID 29765517, 2018). "To investigate the involvement of FoxM1 in the mevalonate pathway, we examined whether the inhibition of the mevalonate pathway might affect the FoxM1 protein expression in human hepatoma cells." (PMID 29765517, 2018). "Although recently it has been reported that miR-216b could inhibit cell growth by targeting FOXM1 in hepatocellular carcinoma and melanoma, the role of miR-216b and the relationship between miR-216b and FOXM1 in cervical cancer remains unclear." (PMID 28978307, 2017). "Interestingly, FOXM1 has been identified in hepatocellular carcinoma as a target of Alternate Reading Frame of the INK4a/ARF locus (CDKN2A), which also encodes p16ink4a." (PMID 26279295, 2016). "Considering the major role of FoxM1 in many types of cancer, miR-320a might be a promising agent to treat other cancers, such as hepatic carcinoma." (PMID 27086911, 2016). "Furthermore, a cell-permeable ARF peptide inhibitor of FOXM1 has been shown to selectively induce apoptosis in human hepatocellular carcinoma cell lines and mouse models." (PMID 24765206, 2014). "In addition, FOXM1 induces metastasis and epithelial-mesenchymal-like transition in hepatocellular carcinoma (HCC)." (PMID 25093142, 2014). "FOXM1 is known to be overexpressed in hepatocellular carcinoma." (PMID 19287496, 2009). "Similar findings in gastric carcinomas and hepatocellular carcinoma (HCC) further support that FOXM1 is required for VEGF-induced angiogenesis in solid tumors." (PMID 39594778, 2024).